ABO (ABO, alpha 1-3-N-acetylgalactosaminyltransferase and alpha 1-3-galactosyltransferase)
Diseases named in the same sentence as ABO in open-access papers (continued):
Sharing a sentence is not in itself a finding about the gene and the disease.
esophageal cancer (5 papers, 2004 to 2024). A primary or metastatic malignant neoplasm involving the esophagus. "Thus, further basic researches are needed to elucidate the association between ABO blood group and the genetic and biological features of esophageal cancer." (PMID 33392080, 2020). "Accruing evidence indicates the involvement of the ABO blood group system in the development or prognosis of many malignancies, including esophageal cancer." (PMID 30406028, 2018). "Therefore, our study is also first time to systematically demonstrate the role of each ABO blood type in predicting the prognosis of patients with esophageal cancer." (PMID 33392080, 2020). "Therefore, we studied a large cohort of southern Chinese patients to clarify the prognostic value of ABO blood group and each ABO blood type for esophageal cancer." (PMID 33392080, 2020). "Previous studies indicated that the ABO blood type was not an independently associated with prognosis of esophageal cancer." (PMID 33392080, 2020). "Nevertheless, ABO blood group has not yet been demonstrated to independently predict survival of esophageal cancer in previous studies." (PMID 33392080, 2020).
hypercoagulable (5 papers, 2021 to 2025). "Integration of ABO phenotype or high-risk genotypes with established thrombophilia markers could improve risk prediction and inform future research on personalized anticoagulation strategies." (PMID 41374354, 2025).
leukemia (5 papers, 2009 to 2024). A malignant (clonal) hematologic disorder, involving hematopoietic stem cells and characterized by the presence of primitive or atypical myeloid or lymphoid cells in the bone marrow and the blood. "Diminished expression of ABH antigens can occur due to variant ABO alleles and hematological malignancies such as leukemia, myelodysplastic syndrome, myeloproliferative disorders, and sometimes Hodgkin’s lymphoma." (PMID 39290944, 2024). "Many previous studies found the ABO blood group to be associated with the risk of malignant diseases compared to normal cells, which led to an existing association between ABO antigens and chronic diseases, including leukemia; however, this association remains uncertain until now." (PMID 38654809, 2024). "Further studies are needed to determine the importance of ABO alterations in leukemia and whether these are causative or an epiphenomenon." (PMID 19274076, 2009). "A comprehensive review was conducted for previous studies revealing the relationship between ABO blood groups and leukemia on the recommended databases, such as Web of Science, Scopus, PubMed, and Google Scholar." (PMID 38654809, 2024). "The present research attempts to examine the possible implications and correlation between leukemia and the distribution and discrepancy of the ABO system." (PMID 38654809, 2024). "The document concludes that studying ABO blood group distributions among leukemia patients showed that the most common blood group in acute leukemia is the A group, while in chronic leukemia, the O group is predominant; more studies are required." (PMID 38654809, 2024). "At present, the impact of donor and recipient ABO statuses on the efficacy of transplantation among leukemia patients remain controversial." (PMID 32280563, 2020). "The suggested origin for these blood group discrepancies is that, in some instances of leukemia, the ABO antigens on the red cell exhibit an epigenetic change of the ABO gene in RBCs due to leukemic cells, resulting in its suppression and subsequent shift in the blood grouping." (PMID 38654809, 2024). "The proposed cause of these changes in blood grouping is due to, in some cases of leukemia, the ABO antigens on the red cell showing an epigenetic modification of the ABO gene in RBCs by leukemic cells, leading to its suppression and subsequent discrepancy in the blood grouping." (PMID 38654809, 2024). "Additionally, since changes at the ABO locus have been associated with changes at other 9q34 loci, it is likely that ABO alterations are not the leukemia causing event but rather a marker of other events occurring at this chromosomal region." (PMID 19274076, 2009).
oral carcinomas (5 papers, 2004 to 2024). "Numerous studies have been conducted to assess ABO blood group and its association with oral cancer, other potentially malignant disorders, and oral submucous fibrosis." (PMID 34181324, 2021). "The present study was intended to fill the knowledge gap and to provide information and evidence for the association between ABO blood group system with oral cancer and other potentially malignant disorders." (PMID 34181324, 2021). "A search was conducted in Medline, Cochrane databases, Google Scholar, Scopus, Web of Science and Directory of Open Access Journals (DOAJ) for studies evaluating ABO blood groups as risk factors for oral cancer and OPMD among cases and controls." (PMID 34181324, 2021). "Suggesting that there was significant loss of ABO antigens in oral cancer patients, moderate loss in OSMF and leukoplakia and mild loss in oral benign lesions." (PMID 32334486, 2020). "In conclusion, there is significant loss of ABO antigens in tissue specimens of oral cancer cases when compared with OSMF, leukoplakia and benign lesions." (PMID 32334486, 2020). "ABO was selected due to reports specifically in oral carcinomas that detected methylation of the gene, loss of expression of these epithelial antigens, and frequent alteration of chromosome 9q34 where the ABO gene resides." (PMID 25859283, 2014). "Human ABO blood group type and the antigenic secretor status are hypothesized to associate with oral diseases including oral cancer." (PMID 38167167, 2024). "The present study was conducted to investigate the expression of ABO (H) antigens in tissue specimens of oral cancer, potentially malignant lesions and conditions and to determine the degree of loss of ABO (H) antigens as a marker of the tumour stage of the patient." (PMID 32334486, 2020). "This study aimed to evaluate the secretor status of ABO antigens of saliva in patients with oral cancers or oral potentially malignant disorders (OPMDs) relative to healthy adults." (PMID 38167167, 2024). "Our interested outcome is the secretor status of the ABO blood group antigens in the saliva in people with oral cancers or oral potentially malignant conditions." (PMID 38167167, 2024). "There are several host risk factors affecting the development of oral cancers such as alcohol consumption, tobacco smoking, nutritional status, viral infections such as human papilloma virus (HPV), and ABO antigens." (PMID 38167167, 2024). "ABO antigens in tissue specimens was substantially reduced in oral cancer cases when compared with OSMF, leukoplakia and oral benign lesions which was statistically significant (P<0.001)." (PMID 32334486, 2020). "The first reports of ABO changes in tumours were described as early as 1930, and changes in expression of blood group antigens in oral carcinomas were reported by Kovarik in 1968, and later confirmed by several other authors." (PMID 32334486, 2020). "These mean values suggest that ABO antigens loss is minimal in benign lesions group, moderate in leukoplakia and OSMF groups and severe in oral cancer group." (PMID 32334486, 2020). "This suggests that ABO glycosyltransferase activity may even play a role in the development of oral cancer." (PMID 38167167, 2024).
Peptic ulcer (5 papers, 2018 to 2025). The term peptic ulcer refers to acid peptic injury of the digestive tract, resulting in mucosal break reaching the submucosa. "In the UK Biobank, ABO, CDX2, CCKBRMUC1, MUC6, FUT2, PSCA, and GAST genes have been identified and found to be associated with peptic ulcer disease." (PMID 36678166, 2023).
pure red-cell aplasia (5 papers, 2018 to 2024). A disease characterized by normocytic, normochromic anemia, low hematocrit, reticulocytopenia, and selective erythroid hypoplasia. "Pure red cell aplasia (PRCA) is a potential complication following allogeneic hematopoietic cell transplantation (allo-HCT) due to major or bidirectional ABO incompatibility." (PMID 39246802, 2024). "In fact, ABO incompatibility can lead to immediate or delayed immunological complications, such as immediate and delayed hemolysis, Pure Red Cell Aplasia (PRCA), impact on the engraftment and, in the end, on the transplanted patient clinical outcome." (PMID 38786038, 2024). "Pure red cell aplasia occurs in up to 30% of all major ABO-incompatible HSCTs." (PMID 33195341, 2020).
red cell aplasia (5 papers, 2017 to 2024). "Here we describe the successful treatment of a therapy-refractory pure red cell aplasia case following ABO-mismatched allogeneic stem cell transplantation with isatuximab." (PMID 39246802, 2024). "Among the 4 patients with pure red cell aplasia (PRCA), 3 received a major ABO mismatched transplant that was the likely cause of the PRCA." (PMID 27816648, 2017). "However, the ABO mismatch between recipient and donor must be taken into account as it may lead to acquired pure red cell aplasia (PRCA), with prolonged transfusion requirement and the risk of iron overload." (PMID 39015495, 2024). "To assess the influence of an ABO mismatch on erythropoietic recovery shortly after SCT, we analyzed reticulocyte recovery because this is not affected by transfusions but is delayed in pure red cell aplasia." (PMID 33330281, 2020).
Thromboembolism (5 papers, 2017 to 2023). The formation of a blood clot inside a blood vessel that subsequently travels through the blood stream from the site where it formed to another location in the body, generally leading to vascular occlusion at the distant site. "This might be how body mass index (BMI) interacts with variants of the F5 and ABO genes (as if X = BMI, Z = F5 SNP, V = ABO SNP) in ventral thromboembolism risk." (PMID 33901204, 2021). "Our findings clearly demonstrate that the rs495828/rs2519093 polymorphism in ABO gene represent an independent risk factor in PNH patients for thromboembolism, the mechanism for the associations probably involved in the regulation of plasma level of vWF and factor VIII." (PMID 29190926, 2017).
colorectal cancer (4 papers, 2015 to 2023). A primary or metastatic malignant neoplasm that affects the colon or rectum. "Hence, the objective of this study is to ascertain the potential influence of ABO and Rh blood groups on the risk, clinicopathological characteristics, and prognosis of colorectal cancer within indigenous communities in India." (PMID 38013340, 2023). "Finally, further clinical studies with longer durations of follow-up are required to be undertaken to accurately identify the link, with an emphasis on the genetic analysis of ABO and Rh blood antigens among colorectal cancer patients." (PMID 38013340, 2023).
endometriosis (4 papers, 2014 to 2023). The growth of functional endometrial tissue in anatomic sites outside the uterine body. "The aim of our study was to determine if the distribution of the ABO and Rh blood groups is associated with endometriosis in women who visited the KAUH Obstetrics and Gynecology Clinic in Jeddah, Saudi Arabia." (PMID 38283422, 2023). "Therefore, the primary aim was to determine whether there is an association between the distribution of ABO and Rh blood groups and the incidence of endometriosis in a cohort from Saudi Arabia and also to evaluate the potential risk factors related to endometriosis among the population." (PMID 38283422, 2023). "There was no significant associationbetween the different stages of endometriosis (I-IV) andfrequency of ABO and Rh blood groups." (PMID 29935066, 2018). "The large sample size used in this study allowed us to assess the relationship between ABO blood type and ovarian reserve while adjusting for confounding factors associated with ovarian reserve, including age, AFC, BMI, subfertility type, and histories of endometriosis and ovarian surgery." (PMID 27462770, 2016). "However, the evidence is not sufficient to confirm/reject the hypothesis that the ABO system could be a genetic risk factor for the development of endometriosis, and further studies on larger samples and with more genetic factors are required." (PMID 38283422, 2023). "Further, no studies have investigated the link between ABO and Rh blood types and endometriosis in Jeddah, Saudi Arabia." (PMID 38283422, 2023).
erythroblastosis fetalis (4 papers, 2018 to 2025). "Hemolytic disease of newborn (HDN) refers to an alloimmune hemolytic disorder in fetuses or newborns caused by incompatibility between the blood types of the mother and the fetus, with Rh and ABO incompatibility being the most common causes (referred to as Rh-HDN and ABO-HDN, respectively)." (PMID 40800598, 2025).
infertile (4 papers, 2013 to 2022). "Several studies conducted to find the association of ABO blood group antigens with anti sperm antibodies in infertile couples." (PMID 24575289, 2013). "This study was done to find any association of ABO blood groups with infertility.In the present study, there was a significant relationship betweenABO blood group andmen infertility." (PMID 24575289, 2013). "In the present study, after excluding infertile women over 35 years, the relationship between the distribution of the ABO blood type and the ovarian reserve was analyzed by Chi-square test." (PMID 36539903, 2022). "The aimof this study was to investigate the distribution of ABO and Rh blood groups in Iranian women with endometriosiswho presented to two referral infertility centers in Tehran, Iran." (PMID 29935066, 2018). "Objective of the present study is to determine the effect of parental ABO blood group on fetal surveillance and men infertility." (PMID 24575289, 2013). "But generally, as a mentioned,there are some contrary results about relationship between ABO blood groups and fertility or infertility." (PMID 24575289, 2013). "The other possible mechanism of ABO-related infertility was its effect on thrombosis, some studies suggested the formation of blood vessels at the maternal-fetal interface may lead to the failure of implantation or placenta, further influent the clinical outcomes of IVF." (PMID 35602516, 2022). "This study explores whether ABO blood type is associated with the clinical outcomes of IVF treatment, history of spontaneous miscarriage, embryo quality parameters, and birth sex, weight, and birth defect rates in Chinese infertile couples." (PMID 35602516, 2022). "Another study has suggested that theremight be some measure of low zone tolerance to ABO antigens on spermatozoa and therefore ABO incompatibility might not significantly contribute to infertility." (PMID 24575289, 2013).
syphilis (4 papers, 2009 to 2025). A contagious bacterial infection caused by the spirochete Treponema pallidum. "The sample was used for ABO blood grouping, syphilis, hepatitis B, and chlamydia screening using serological assays." (PMID 41458404, 2025). "ABO and RhD typing and screening for HIV and syphilis were undertaken in all transfused blood." (PMID 19682362, 2009).
thrombotic disease (4 papers, 2014 to 2023). The formation of a blood clot in the lumen of a vessel or heart chamber; causes include coagulation disorders and vascular endothelial injury. "In general, ABO is a pleiotropic locus that is related to thrombotic diseases, such as VTE." (PMID 36295093, 2022).
acute coronary syndrome (3 papers, 2016 to 2023). Signs and symptoms related to acute ischemia of the myocardium secondary to coronary artery disease. "The role of ABO gene polymorphisms in acute coronary syndrome (ACS) and lipid metabolism is increasingly recognized." (PMID 37334748, 2023).
acute myeloid leukemia (3 papers, 2017 to 2024). Acute myeloid leukemia (AML) is a group of neoplasms arising from precursor cells committed to the myeloid cell-line differentiation. "Here we report on a 61-year-old woman who received an ABO-mismatched, HLA-matched unrelated donor hematopoietic cell transplantation from a presumably healthy donor for a diagnosis of acute myeloid leukemia (AML)." (PMID 28316846, 2017).
allergic reactions (3 papers, 2014 to 2024). "This is possibly because of tolerable agglutination titers, use of O-type pRBCs to avoid ABO incompatibilities, and extensive filtering and washing of pRBCs to reduce post-transfusion allergic reactions." (PMID 38994362, 2024). "Inflammation is addressed in transfusion safety essentially by measures to avoid three types of hazards also linked with an Ag/Ab conflict: ABO mismatches (which create a potentially lethal cytokine storm), TRALI, and severe allergic reactions." (PMID 24830754, 2014).
Arterial thrombosis (3 papers, 2012 to 2016). The formation of a blood clot inside an artery. "The ABO locus has also been associated with arterial thrombosis in studies of MI." (PMID 23133757, 2012). "Thus these and other uncharacterised ABO-expressing platelet proteins may also act as potential functional modulators of the ABO associations with arterial thrombosis and cardiovascular events." (PMID 26860707, 2016). "Thus these and other uncharacterized ABO-expressing platelet proteins may also act as potential functional modulators of the ABO associations with arterial thrombosis and cardiovascular events." (PMID 23133757, 2012). "The identification of the ABO locus through its association with vWF and FVIII points the way for mechanistic work to understand better the role of these 2 coagulation factors in end-stage arterial thrombosis." (PMID 23381943, 2013). "Whether VWF in platelets (a relatively abundant source) undergoes any modification by ABO remains controversial; such modification could alter platelet production and subsequent turnover of VWF, particularly locally during platelet-driven arterial thrombosis, although this remains to be established." (PMID 23133757, 2012).
bladder tumor (3 papers, 2024). "However, an analysis at the allelic level revealed a statistically significant association between certain alleles of the ABO blood group system and urinary bladder tumors, clinical or histological stage, and recurrence rate, respectively." (PMID 39040623, 2024). "Previous investigations showed a decrease in ABO gene expression in ovarian tumor tissues and human bladder tumors." (PMID 38840912, 2024). "In contrast, in bladder tumor, the lack of ABO (H) antigen is a well-documented event and was associated with tumor progression and recurrent disease which are attributed to the loss of relevant GT activities due to downregulation of ABO (H) mRNA transcripts." (PMID 38670309, 2024).
cardioembolic stroke (3 papers, 2013 to 2024). "Early studies reported that ABO gene variants (rs651007, rs643434, and rs505922) are associated with LAA and cardioembolic stroke in the European population." (PMID 27542834, 2016). "ABO gene variants are associated with large-vessel and cardioembolic stroke but not small-vessel disease." (PMID 23381943, 2013).
cervical cancer (3 papers, 2023 to 2025). A primary or metastatic malignant neoplasm involving the cervix. "The relationship between the ABO and Rh system with cervical cancer has been studied since the 1950s, though without obtaining clear results." (PMID 39132152, 2024).
colon tumor (3 papers, 2017 to 2023). "Previous studies demonstrated that the proliferation and motility of colon tumor cells are highly associated with the expression of ABO blood type antigen, particularly blood type antigen A." (PMID 37296868, 2023). "We showed in this study that lentiviral vectors carrying ABO blood group antigens successfully inhibited tumor growth in breast and colon cancer by causing the body's immune response." (PMID 34376742, 2021). "Experimental studies have demonstrated that the expression of ABO blood type antigens on colon tumor cells, and the cell proliferation and motility are highly associated with the expression of blood type antigen A." (PMID 28880901, 2017).